IFNAR1 (interferon alpha and beta receptor subunit 1)
Description:
Together with IFNAR2, forms the heterodimeric receptor for type I interferons (including interferons alpha, beta, epsilon, omega and kappa). Type I interferon binding activates the JAK-STAT signaling cascade, resulting in transcriptional activation or repression of interferon-regulated genes that encode the effectors of the interferon response. Mechanistically, type I interferon-binding brings the IFNAR1 and IFNAR2 subunits into close proximity with one another, driving their associated Janus kinases (JAKs) (TYK2 bound to IFNAR1 and JAK1 bound to IFNAR2) to cross-phosphorylate one another. The activated kinases phosphorylate specific tyrosine residues on the intracellular domains of IFNAR1 and IFNAR2, forming docking sites for the STAT transcription factors. STAT proteins are then phosphorylated by the JAKs, promoting their translocation into the nucleus to regulate expression of interferon-regulated genes. Can also act independently of IFNAR2: form an active IFNB1 receptor by itself and activate a signaling cascade that does not involve activation of the JAK-STAT pathway (By similarity).
Synonyms: IFN-R-1; CRF2-1; IFNAR; IFRC; AVP; IFN-alpha-REC; IFNBR; IMD106
Tractability: Antibody: an approved drug acts on it; UniProt places it where antibodies can reach, with high confidence; its Gene Ontology location is reachable by antibodies, with high confidence; UniProt predicts a signal peptide or a membrane-spanning region. PROTAC: UniProt records ubiquitination sites on it; ubiquitination databases record sites on it; a small molecule that binds it is known. Other modalities: an approved drug acts on it.
Target class: Membrane receptor
Gene: Protein-coding gene on chromosome 21 (33,324,387 to 33,359,864, forward strand). Ensembl gene ENSG00000142166.
Subcellular location: Cell membrane (Isoform 1); Late endosome; Lysosome
Pathways (Reactome):
Disease: Evasion by RSV of host interferon responses; Potential therapeutics for SARS; SARS-CoV-2 activates/modulates innate and adaptive immune responses
Immune System: Interferon alpha/beta signaling; Regulation of IFNA/IFNB signaling
Gene Ontology:
Molecular function: cytokine binding; JAK pathway signal transduction adaptor activity; protein binding; type I interferon receptor activity; type I interferon binding; interferon receptor activity
Biological process: cell surface receptor signaling pathway via JAK-STAT; cellular response to interferon-beta; positive regulation of cellular respiration; type I interferon-mediated signaling pathway; cellular response to interferon-alpha; cellular response to virus; response to lipopolysaccharide; response to virus; cytokine-mediated signaling pathway; regulation of receptor signaling pathway via JAK-STAT
Cellular component: late endosome; lysosome; plasma membrane; receptor complex
Genetic constraint (gnomAD): Loss-of-function variants: 10 observed, 9.39 expected, observed/expected ratio (o/e) 1.07, 90% interval 0.65 to 1.73. That is too few expected variants to judge how well the gene tolerates losing a copy. Missense variants: 102 observed, 112.7 expected, observed/expected ratio (o/e) 0.91, 90% interval 0.77 to 1.07. Synonymous variants: 47 observed, 45.16 expected, observed/expected ratio (o/e) 1.04, 90% interval 0.82 to 1.33.
Gene-disease validity (ClinGen):
ClinGen rates the evidence that IFNAR1 causes each of these diseases.
immunodeficiency 106, susceptibility to viral infections (autosomal recessive): Definitive.
Homologues: Orthologues: chimpanzee IFNAR1 (99% identical), macaque IFNAR1 (87% identical), dog IFNAR1 (68% identical), pig IFNAR1 (67% identical), guinea pig IFNAR1 (56% identical), rabbit IFNAR1 (56% identical), rat Ifnar1 (50% identical), mouse Ifnar1 (49% identical), zebrafish il10rb (17% identical). Paralogues in human: IL10RB (14% identical), IL20RA (13% identical), IFNLR1 (12% identical), IFNGR1 (11% identical), IL10RA (10% identical), IFNGR2 (10% identical), IFNAR2 (10% identical), IL20RB (10% identical), IL22RA1 (9% identical), IL22RA2 (9% identical), F3 (7% identical).
Diseases named in the same sentence as IFNAR1 in open-access papers:
IFNAR1 is named in the same sentence as 287 diseases in open-access papers, as found by Europe PMC text mining. Sharing a sentence is not in itself a finding about the gene and the disease. The quoted sentences say what the papers report.
viral infection (208 papers, 2008 to 2026). "We systematically analyzed all monoallelic and biallelic, and rare and common IFNAR1 variants in our cohort of patients with viral diseases." (PMID 39680367, 2025). "Individuals with AD IFNAR1 deficiency are vulnerable to various viral diseases, including critical COVID-19 pneumonia and JEV encephalitis." (PMID 39680367, 2025). "We first created an interferon (IFN)-alpha/beta receptor alpha chain (IFNAR1)-deficient human embryonic kidney 293 (HEK293) cell line (clone 14) via CRISPR-Cas9 to eliminate the confounding effects of type I IFN signaling on viral infection and propagation." (PMID 40853130, 2025). "Surprisingly, only a few viral diseases have been reported in patients with IFNAR1 or IFNAR2 deficiency." (PMID 36719370, 2023). "For example, mice with a deficiency in the IFN-I receptor subunit 1 (Ifnar1-/-) are highly susceptible to various viral infections in multiple organs, including the CNS." (PMID 36325336, 2022). "Alternatively, mucormycosis in this patient was secondary to an undocumented viral infection due to the IFNAR1 deficiency." (PMID 35091979, 2022). "The penetrance of severe LAV and WT viral disease appears to be incomplete in patients with IFNAR1 or IFNAR2 deficiency." (PMID 35442418, 2022). "In contrast, the molecular target of anti-IFNAR1 is a key element of innate and adaptive antiviral immunity, which suggests why anti-IFNAR1 therapy is associated with a higher risk for certain viral infections such as HZ." (PMID 36119023, 2022). "Rs2257167 appears to increase IFNAR1 expression and is associated with increased protection against viral infection." (PMID 34917078, 2021). "Several murine models of antibody-mediated IFN-I receptor (IFNAR) blockade or genetic ablation of IFN-I signaling (IFNAR1 KO) demonstrated the central pathogenic role played by IFN-I during viral infections." (PMID 34473195, 2021). "We chose to use the Ifnar1-/- mice, because, like other viral infections, coronaviruses encode genes which dampen or block the type I IFN response creating a more susceptible environment for the establishment of infection." (PMID 33326500, 2020). "Antibody responses are important for keeping persistent viral infections in check, making loss of humoral immunity in CD11c-Ifnar1-/- mice a potential basis for viral persistence." (PMID 27327515, 2016). "This fits with the observation that IFNAR1-KO mice (which have an intact IFN-λ system) exhibit extreme susceptibility to many neurotropic viral infections." (PMID 18369468, 2008). "Autosomal recessive deficiency of the IFNAR1 or IFNAR2 chain of the human type I IFN receptor abolishes cellular responses to IFN-α, -β, and -ω, underlies severe viral diseases, and is globally very rare, except for IFNAR1 and IFNAR2 deficiency in Western Polynesia and the Arctic, respectively." (PMID 39680367, 2025). "The penetrance of severe LAV and naturally acquired viral diseases seems to be incomplete, as previously seen in patients with AR complete IFNAR1 or IFNAR2 deficiency, whereas penetrance is higher for infections with certain viruses, such as SARS-CoV-2 than for HSV-1." (PMID 39680367, 2025). "In this context, we tested the hypothesis that there might be new genetic forms of inherited IFNAR1 deficiency in patients with life-threatening viral diseases." (PMID 39680367, 2025). "During systemic MCMV infection, MyD88-deficient mice were more resistant to viral infection than Ifnar1-KO mice, showing that other cell types contributed to IFN-I-dependent antiviral defense in the absence of pDCs, consistent with the STING-dependent contribution of stromal cells to this function." (PMID 38777879, 2024). "Next, we examined whether Ifnar1 k/o or Stat2 k/o augments the susceptibility of PK-15 cells to viral infection in the presence of IFNβ." (PMID 37939052, 2023).
viral infection (continued). "Mice deficient in the production of T and B lymphocytes (RAG-1−/− strain) and knockout mice for the Ifnar1 allele, lacking type I interferon receptor function, which results in a reduced immune response and an increased susceptibility to viral infection (IFN⍺R1−/− (IFNAR)), were evaluated." (PMID 37766210, 2023). "Development of an IFNAR1-deficient mouse model demonstrated that the loss of type I IFN signaling due to the lack of the responsive IFN receptor renders mice highly susceptible to virus infections." (PMID 37766322, 2023). "Individuals with autosomal recessive IFNAR1 deficiency described thus far, including our patient, were aged 6 months to 38 years and, surprisingly, had suffered from relatively few viral infections, consistent with the clinical features of patients with IFNAR2 deficiency." (PMID 35091979, 2022). "However, it is not possible to draw any firm conclusion about the penetrance of IFNAR1 deficiency for most viral diseases at the moment, owing to the small number of patients diagnosed and the associated ascertainment bias." (PMID 35442418, 2022). "Although the patients with IFNAR1 deficiency can be otherwise healthy until adulthood, they may still suffer from a high mortality in an episode of viral infection (3/10 dead due to viral infection, 30%)." (PMID 35091979, 2022). "Interestingly, interferon-β (IFN-β) treatment was able to induce lncRNA ISR expression, and induction of lncRNA ISR by viral infection was nearly abolished in host deficient of IFNAR1, a type I IFN receptor." (PMID 31623059, 2019). "Adoptive transfer of wild-type bone marrow cells into IFNAR1-deficient mice demonstrated that receptor deficiency in the stromal compartment was sufficient to increase the proliferation of EpCam + MHC-II + CD49flow type II alveolar epithelial cells at the late stage of virus infection." (PMID 37766322, 2023). "Thus, the risk for viral infections could be higher with therapeutic IFNAR1 inhibition compared to therapeutic BAFF inhibition." (PMID 36119023, 2022). "It provides indirect evidence that the onset and progression of narcolepsy may be associated with abnormal immune response following a virus infection, in which the IFNAR1 dysfunction likely plays an important role, finally leading to the destruction of hypocretin neurons due to immune attack." (PMID 32669953, 2020). "It is obvious that the advent of Ifnar1–/– mice undoubtedly constituted a major step forwards in allowing researchers to easily and rapidly study the pathogenesis of clinical isolates during a potential outbreak situation, as these animals are more susceptible to viral infections." (PMID 29511140, 2018). "Autosomal recessive interferon alpha and beta receptor subunit 1 (IFNAR1) deficiency is a rare and heritable inborn error of immunity (IEI) predisposing individuals to severe and life-threatening viral infections." (PMID 42116640, 2026). "Missense mutations were identified in the IFN-α receptors 1 and 2 (IFNAR1 and IFNAR2), the IFNGR2, the IFNLR1, receptors critical for the response to viral infections." (PMID 41522351, 2026). "To further explore the molecular differences between WT and IFNAR1-KO MDCK cells in response to viral infection, we performed high-throughput RNA sequencing following H1N1 influenza virus infection." (PMID 40872812, 2025). "Autosomal recessive (AR) complete IFNAR1 deficiency has been shown to underlie adverse reactions to vaccination with live-attenuated viruses (LAV), including measles–mumps–rubella (MMR) and yellow fever (YF)." (PMID 39680367, 2025). "The RT-qPCR results showed that the upregulation of RNF149 expression induced by viral infection was suppressed in the IFNAR1 antibody-blocking group." (PMID 40245000, 2025). "NF-κB inhibitors (JSH-23 and QNZ), JAK1 inhibitor itacitinib, and Ifnar1 deficiency blocked viral infection-induced DTX3L expression, suggesting that viruses activate NF-κB and IFNAR-JAK to upregulate DTX3L." (PMID 40595467, 2025).
viral infection (continued). "Both C57BL/6 IFNAR1−/− and A129 IFNAR1−/− mice lack the type I interferon (IFN) receptor, rendering them highly susceptible to viral infections." (PMID 41157597, 2025). "LOF variants of IFNAR1 and IFNAR2 are common in Western Polynesia and the Arctic, where they underlie viral disease in homozygotes." (PMID 39680367, 2025). "As a starting point to investigate the regulation of LGP2 expression, we compared HeLa-WT and HeLa IFNAR1-KO cells for their responses to various stimuli mimicking viral infections." (PMID 41171864, 2025). "Next, the influence of p22 on the endogenous IFNAR1 level was determined via p22 overexpression and viral infection." (PMID 40668839, 2025). "It is known that, the phosphorylation and ubiquitination of IFNAR1 are upregulated upon viral infection, followed by endocytosis and lysosomal degradation of IFNAR1." (PMID 40668839, 2025). "The IFNAR1-JAK-STAT1/2 pathway is critical for the upregulation of RLR expression during viral infection." (PMID 38278841, 2024). "And our present study showed that an IFN I-inducible gene, PVRL4, was robustly and lastingly upregulated in host cells treated by either IFN-I or numerous viral infections in an IFNAR1-dependent manner." (PMID 38368366, 2024). "This was tested in our current study by the identification of homozygous variants in IFNAR1 and DOCK8 in a young individual presenting with a history of severe and recurrent viral infections." (PMID 39098944, 2024). "In contrast, MyD88 and IFNAR1 KO mice exhibited resistance to a lethal dose (1×105 pfu) of the Delta P80 virus infection." (PMID 39652608, 2024). "Our data have demonstrated that MyD88 or IFNAR1 KO mice are highly resistant to lethal the Delta P80 virus infection compared with WT mice." (PMID 39652608, 2024). "Total RNA was extracted from the samples and analyzed using RT-qPCR to confirm the impact of IFNAR1 knockout on the activation of type I IFN pathway during viral infection." (PMID 39100665, 2024). "Treatment with viral genomic RNA, poly (I:C), or interferons (IFNs) significantly stimulated LINC02574 expression, while RIG-I knockdown and IFNAR1 knockout significantly decreased LINC02574 expression after viral infection or IFN treatment." (PMID 37108410, 2023). "This was subsequently validated using IFNAR1 knockout cells, which demonstrated diminished expression of circMerTK following the viral infection." (PMID 36847523, 2023). "The results demonstrated that PK-15 Ifnar1 k/o cells reconstituted with IFNAR1 (WT) showed resistance to viral infection, similar to that in normal PK-15 cells." (PMID 37939052, 2023). "As a ligand, the N-terminus of secreted LRPAP1 binds with the extracellular domain of IFNAR1 that triggers the receptor ubiquitination and degradation and promotes virus infection both in vitro, ex vivo in the mouse brain, and in vivo in newborn mice." (PMID 37743411, 2023). "This systematic review aimed to describe SNV in IFNAR1 and IFNAR2 genes associated with a high risk of viral infection or clinical relevance in COVID-19." (PMID 38003785, 2023). "More importantly, a synthesized peptide derived from the N-terminal sequence, RAPD1P1, potently inhibited IFNAR1 degradation and promoted viral infections." (PMID 37743411, 2023). "Our results illustrated that PK-15 Ifnar1 k/o and PK-15 Stat2 k/o cells were susceptible to HIV-1–based reporter virus infection upon IFNβ treatment." (PMID 37939052, 2023). "Type I IFNs are activated following influenza infection and the role of IFNAR1 in the Type I IFN response to viral infection has been described in detail for mammalian hosts, but such mechanism is still unclear in the chicken." (PMID 35056582, 2022). "We describe here seven affected individuals from five unrelated kindreds of western Polynesian ancestry who experienced severe LAV and viral infections and were found to be homozygous for the same LOF variant of IFNAR1." (PMID 35442418, 2022).
viral infection (continued). "Type I IFNs and IFNAR1-mediated signaling induce immune responses to bacterial and viral infection, implying a potential relationship between AAA disease and pathogen-driven immune responses." (PMID 36291750, 2022). "The difference in cytopathy shows the promoting effect of IFN inhibitor and IFNAR1 silencing on viral infection." (PMID 35062253, 2021). "Here we used a lethal acute mouse model of viral infection to show that IFNAR mediates protection mostly by signaling in hematopoietic cells, as indicated by results obtained with Ifnar1-/- BMC and Cre-LoxP conditional deletions." (PMID 34015056, 2021). "Viral infection induced metabolic alterations of the liver that depended on the interferon alpha/beta receptor (IFNAR1)." (PMID 31784108, 2019). "The role of type I IFN signaling in regulating host susceptibility to both viral infections and BSI has been only examined with respect to IFNAR1 deficiency." (PMID 30473701, 2018). "Approaches in which Ifnar1, a pathway response against viral infection, is disrupted, either through the administration of a blocking antibody or the use of Ifnar1 knocked-out mice, are a suitable CZS model." (PMID 30142150, 2018). "Finally, the same IFNAR1 mutation is associated with increased susceptibility to viral hepatitis, revealing a previously unknown divergent function of type I IFNs in bacterial and viral infection in humans." (PMID 29311663, 2018). "Here, for the first time we found that apigenin can inhibit the ubiquitination and degradation of IFNAR1, suggesting its potential as a new adjuvant for improving the efficacy of type I IFNs in the treatment of viral infections or cancers." (PMID 27356910, 2016). "To investigate the long-term effects of transient blockade of IFNAR1, we administered the IFNAR1-specific antibody on day −1, 0, and 1 after infection as performed previously and monitored the course of chronic viral infection for 30 days." (PMID 26588782, 2015). "Two different mechanisms have been proposed to explain why IFNAR1 protein is degraded in viral infection." (PMID 25961570, 2015). "Both IFNAR1 and IFNAR2 are required for the initiation of IFN-I-dependent signals, as mice deficient in either one are highly susceptible to viral infections." (PMID 25400632, 2014). "IFNα/β exerts antiviral activity by binding to the IFNAR1/IFNAR2 complex during viral infection." (PMID 40001503, 2025). "The results showed that knockdown of RNF149 reduced viral infection in Ifnar1+/+ cells." (PMID 40245000, 2025). "These targets include STAT3, which is a key regulator of the host's innate response to viral infections, IFNAR1, a vital antiviral factor, MDA5, an RNA antiviral sensor, and protein kinase TBK1, which participates in the induction of type I interferons in response to viral replication." (PMID 38501860, 2024). "Furthermore, the elevated viral titers in IFNAR1-knockout cells hold immense potential in controlling bovine viral infections." (PMID 39100665, 2024). "Moreover, we can leverage the IFNAR1 knockout cell model for virus screening and identification, thereby providing technical support for the prevention and control of bovine viral infections." (PMID 39100665, 2024). "IFNAR1 controls dendritic cell responses to viral infections, notably Influenza-A." (PMID 37188663, 2023). "Patients with recessive and complete deficiencies in TLR7, IRF7, or the type I IFN receptor (heterodimeric IFNAR, encoded by IFNAR1 and IFNAR2) have impaired type I IFN immunity and are at risk of life-threatening viral infections, including COVID-19 pneumonia." (PMID 36342455, 2023). "The reconstitution of PK-15 Ifnar1 k/o cells with WT IFNAR1, but not with IFNAR1 carrying the W70C mutation, restored the cells’ resistance to viral infection and ISG induction." (PMID 37939052, 2023).